DCN (decorin)
Diseases named in the same sentence as DCN in open-access papers (continued):
Sharing a sentence is not in itself a finding about the gene and the disease.
bladder cancer (17 papers, 2012 to 2026). "Increased secretion of decorin in the MB49/MB49-I murine bladder cancer model and in muscle-invasive tumours was associated with the promotion of angiogenesis and tumour cell invasiveness." (PMID 29207682, 2017). "It is also possible that the antitumour effect of decorin on bladder cancer is mediated via decorin-associated tumor suppressor gene mitostatin, whose activity is reduced in advanced bladder cancer alleviating growth and spread of neoplastic cells." (PMID 24146840, 2013). "In addition, high DCN expression has been associated with stem-like characteristics of chemoresistance and invasion in oral and bladder cancers." (PMID 34253873, 2021). "Finally, our data demonstrate that decorin is associated with progression and promotes invasiveness in human bladder cancer, as proposed from our analysis of a mouse invasive bladder tumour cell variant." (PMID 24142880, 2013). "Furthermore, we have demonstrated that transduction of cultured human bladder cancer cells with a decorin adenoviral vector causes a significant inhibition in the proliferation of the cells in vitro." (PMID 24146840, 2013). "They described tumour cells as being devoid of DCN, which is in contrast to our study, but DCN has also been shown to be upregulated in tumour cells of more aggressive bladder cancer subtypes." (PMID 41392017, 2026). "As shown in bladder cancer cells, decorin binds with similar affinities both the IGF1R and IGF1 at distinct sites and inhibits IGF1-mediated IGF1R phosphorylation, without affecting IGF1R protein levels." (PMID 33673232, 2021). "The expression of decorin is markedly decreased in several malignancies, such as cancers of the bladder, breast, and colon." (PMID 32824864, 2020). "In this study, we have examined decorin expression by human bladder cancer cells both in vivo and in vitro." (PMID 24146840, 2013). "Next we examined the effect of targeted decorin transduction on the proliferation of human bladder cancer cells in vitro." (PMID 24146840, 2013). "We have also shown that adenovirus-mediated decorin gene transduction of human bladder cancer cell lines markedly inhibits their proliferation." (PMID 24146840, 2013). "Based on our results, biglycan expression is detected in human bladder cancer cells which lack decorin expression." (PMID 24146840, 2013). "In conclusion, we have shown that human bladder cancer cells are totally devoid of decorin expression." (PMID 24146840, 2013). "First, we evaluated the previous data regarding decorin gene expression in different cancers with special reference to bladder cancer utilizing the publicly available GeneSapiens databank." (PMID 24146840, 2013). "Next, we localized decorin mRNA and decorin immunoreactivity in our own extensive radical cystectomy patient cohort of human bladder cancer tissue samples using ISH with DIG-labeled decorin probes and a polyclonal decorin antibody, respectively." (PMID 24146840, 2013). "When bladder cancer cells were transfected with a decorin adenoviral vector, their proliferation was significantly decreased." (PMID 24146840, 2013). "The ISH analyses with DIG-labeled RNA probes for decorin clearly demonstrated that invasive bladder carcinoma cells were totally devoid of decorin mRNA in all bladder cancer tissue samples." (PMID 24146840, 2013). "We also examined the effect of decorin gene transduction on the proliferation of human bladder cancer cells in vitro." (PMID 24146840, 2013). "This was also true for human bladder cancer, although in malignant bladder tissue decorin expression was decreased compared to normal bladder tissue." (PMID 24146840, 2013). "In this study, we examined the expression of decorin by human bladder cancer cells both in vivo and in vitro." (PMID 24146840, 2013). "In bladder cancer, which is the 9th most common cancer diagnosis worldwide, the expression of decorin has previously been shown to be decreased." (PMID 24146840, 2013).
bladder cancer (continued). "In this study we clarified decorin expression by human bladder cancer cells both in vivo and in vitro." (PMID 24146840, 2013). "All together, these studies suggested that decorin inhibits expression and activity of IGF-R in bladder cancer and that its loss is permissive for bladder cancer progression to invasive disease." (PMID 24223213, 2013). "However, in gastric cancer, head and neck cancer, bladder cancer, and endometrial cancer, DCN is a predictor of poor prognosis, as determined by bioinformatics analyses." (PMID 34496868, 2021). "Thus, the mechanisms blocking decorin expression by human bladder cancer cells remain to be elucidated." (PMID 24146840, 2013). "Thus, the GeneSapiens results regarding decorin expression in human bladder cancer specimens reflect the quality of the original tissue samples included in the database, i.e., in addition to cancer cells the samples contain various amounts of stromal tissue." (PMID 24146840, 2013). "In addition, the effect of adenovirus-mediated decorin expression on human bladder cancer cells in vitro was examined." (PMID 24146840, 2013). "Thus, both SLRPs, decorin and biglycan, appear to be inhibitory but are differentially regulated in bladder cancer." (PMID 24223213, 2013). "Although several studies have examined decorin expression in various cancers including bladder cancer, there is some uncertainty whether different cancer cells express it or not." (PMID 24146840, 2013). "In addition, we unravel decorin as a new unexpected player in bladder cancer progression, acting both on angiogenesis and on tumour cell invasiveness." (PMID 24142880, 2013). "To determine whether DCN could play similar pro-tumoural functions in human bladder tumours as in the MB49-I mouse model, we first analysed expression of DCN mRNA in human bladder carcinoma cell lines." (PMID 24142880, 2013). "Decorin may thus offer the potential for therapeutic exploitation in advanced bladder cancer." (PMID 24142880, 2013). "Therefore, by using RT-qPCR we next examined whether cell lines representing different grades of human bladder cancer express decorin." (PMID 24146840, 2013). "On the contrary, decorin enhances IGF1-evoked IRS-1 degradation and inhibits Akt and MAPK activation, thus blunting the ability of the IGF1R to promote ligand-evoked bladder cancer cells migration and invasion." (PMID 33673232, 2021). "We used human bladder cancer cell lines RT4 and T24 and a decorin adenoviral vector for this purpose." (PMID 24146840, 2013). "In the light of the present findings it is therefore interesting that decorin inhibits motility and that BGN inhibits proliferation of bladder cancer cells." (PMID 24223213, 2013). "This study provided evidence that decorin is down-regulated and confirmed that IGF-R is up-regulated in high grade bladder cancers." (PMID 24223213, 2013). "In this study, human bladder cancer cell lines RT4 (gradus I) and T24 (gradus III) were transduced with a decorin adenoviral vector which resulted in an identical decrease in cell proliferation, identical to MCF-7 cells." (PMID 24146840, 2013). "Studies have found that human bladder cancer cells do not express decorin in vivo or in vitro, and that decorin expression is reduced in malignant human bladder tissue samples." (PMID 32596162, 2020). "Significantly, decorin exposure of bladder cancer cells considerably reduced IGF-I-induced IGF-IR and caveolin-1 colocalization, suggesting that decorin may affect either IGF-IR internalization or divert the receptor into a different endocytic compartment." (PMID 25566192, 2014). "In conclusion, in this study we have shown that human bladder cancer cells do not express decorin either in vivo or in vitro, and that decorin expression in malignant human bladder tissue resides merely in the areas of original, non-malignant stroma." (PMID 24146840, 2013).
bladder cancer (continued). "Both the ISH results and the RT-qPCR assays clearly demonstrated that human bladder cancer cells are not able to express decorin either in vivo or in vitro." (PMID 24146840, 2013). "The SLRP decorin, which is closely related to BGN, has recently been studied in bladder cancer." (PMID 24223213, 2013). "Based on these assays we were not able to detect DNA methylation in the decorin gene promoter in any of the bladder cancer cell lines examined." (PMID 24146840, 2013). "Taken together, our results indicate that the lack of decorin expression by bladder cancer cells offers a possibility for using decorin based therapies in human urothelial malignancies." (PMID 24146840, 2013). "The lack of decorin expression by bladder cancer cells was shown not to be due to the methylation of the proximal promoter region of the decorin gene." (PMID 24146840, 2013). "We have also shown that the lack of decorin expression by human bladder cancer cells is not due to the methylation of the proximal promoter regions of the decorin gene." (PMID 24146840, 2013). "In contrast, IHC analysis of the samples for another small leucine-rich proteoglycan, namely biglycan, revealed that decorin negative areas in invasive bladder cancer tissue were positive for biglycan immunoreactivity." (PMID 24146840, 2013). "However, our results indisputably demonstrated that methylation of decorin gene promoter does not play a role in human bladder cancer." (PMID 24146840, 2013). "Our in vivo results showed that human bladder cancer cells do not express decorin." (PMID 24146840, 2013). "The results showed that none of the urinary bladder cancer cell lines, including RT-4 (originally grade I urothelial cancer), 5637 (grade II), and T24 (grade III) expressed decorin." (PMID 24146840, 2013).
liver fibrosis (17 papers, 2014 to 2025). "Our study used HSCs to target DCN gene nanoliposomes for the first time to explore the effect and mechanism of DCN intervention in liver fibrosis." (PMID 33415158, 2020). "This study aimed to investigate the effect of bile duct-targeting lecithins- (PC-) coupled decorin (DCN) (PC-DCN) nanoliposomes against liver fibrosis in vitro and in vivo." (PMID 33415158, 2020). "In our secretome analyses of the NPC cultures, Decorin, a well-known endothelial-produced repressor of liver fibrosis and local inhibitor of TGF-β and c-Met, was significantly increased in group IIP." (PMID 31416480, 2019). "In HCC, decorin gene knockout enhanced experimental hepatic fibrosis and impaired the healing of hepatic fibrosis in mice." (PMID 30297672, 2018). "In decorin KO mice, liver fibrosis induced by thioacetamide was enhanced and the tissue repair delayed." (PMID 27547834, 2016). "Decorin also reduces liver fibrosis after CCl4-induced liver injury." (PMID 33415158, 2020). "Considering these overlapped observations, it might be possible that CS/DS-E attached to decorin may bear some part of functions of decorin proteoglycan in liver fibrosis." (PMID 27547834, 2016). "Decorin and decorin mRNA were reported to increase in the liver fibrosis." (PMID 27547834, 2016). "Decorin is a secreted proteoglycan that has a dual role in liver fibrosis." (PMID 27672655, 2016). "It has been also reported the role of decorin (a SLRP member protein) in extracellular matrix of liver fibrosis as inhibitor of TGF-β, the most powerful profibrotic cytokine, and studies suggest the presence of other SLPR members, such as CHAD, in attenuating TGF-β bioactivity." (PMID 26375394, 2015). "In addition, decorin has been found to act protective against liver fibrosis by attenuating TGF-β1 signaling." (PMID 24950767, 2014). "In contrast, aged mice exhibited hepatic fibrosis, with increased collagen deposition and upregulation of genes related to fibrosis (Acta2, MMP2, TGF-ß1, and Col1a2), cirrhosis (CXCR4, SOX9, DCN, and MFAP4), and cancer (Bcl2, CDKN2a, c-Myc, and Fn1)." (PMID 39851554, 2025). "Another study showed that in hepatic fibrosis, decorin, a TGF-β inhibitor, was used for priming MSCs for hepatic fibrosis/cirrhosis." (PMID 38167146, 2024). "As a biglycan, decorin is able to modulate TLR2- and TLR4-mediated signaling and play a role in inflammation; however, our knowledge about decorin and (HCV-induced) liver fibrosis remains piecemeal." (PMID 34065048, 2021). "On the other hand, in thioacetamide-induced liver fibrosis, liver fibrosis was enhanced and the tissue repair delayed in decorin KO mice, and MMP-9 activity was lower in decorin KO mice." (PMID 27547834, 2016). "Furthermore, we examined the relative mRNA expression levels of key markers related to hepatic fibrosis (Acta2, Cola2, TGF-β1, and MMP2), cirrhosis (CXCR4, SOX9, DCN, and MFAP4), and cancer (Bcl2, CDKN2a, c-Myc, and Fn1) across the experimental groups." (PMID 39851554, 2025). "In our study, DCN was up-regulated in kidney fibrosis and it was not significantly altered in liver fibrosis." (PMID 35159124, 2022). "Indeed, the role of DCN on suppressing TGF-β-driven scar formation has been well established in numerous disease models such as renal, lung, and hepatic fibrosis and in skin wound healing, in addition to RDEB." (PMID 32497513, 2020).
lung fibrosis (17 papers, 2010 to 2025). "The purpose of this study was to generate human umbilical cord MSCs (HUC-MSCs) that overexpress DCN and to investigate the safety, mechanism, and effectiveness of using these cells to cure pulmonary fibrosis caused by bleomycin (BLM)." (PMID 40438789, 2025). "Lower decorin and higher biglycan levels correlate with increased disease severity, emphasizing their potential to identify patients at risk for lung fibrosis and guide clinical management." (PMID 39906348, 2024). "Decorin deficiency has been shown to decrease airway resistance and increase lung compliance but decorin over-expression inhibits the development of lung fibrosis, presumably at least partly through its inhibition of TGF-β activity." (PMID 20300191, 2010). "A reduction in decorin levels can heighten the susceptibility to lung fibrosis." (PMID 39906348, 2024). "Eggshell membrane and its major components, LYZ and ovotransferrin, enhance the secretion of decorin—a key endogenous antifibrotic mediator—from lung fibroblasts, and ameliorate bleomycin-induced pulmonary fibrosis." (PMID 41009682, 2025). "Our study demonstrated that MSCs overexpressing DCN can enhance the therapeutic effect on BLM-induced pulmonary fibrosis in rats by inhibiting inflammation and fibrosis deposition in the lung tissue and allowing rats to regain body weight." (PMID 40438789, 2025). "Accordingly, overexpression of decorin in murine disease models was sufficient to protect mice from TGFβ overexpression-induced lung fibrosis." (PMID 41362624, 2025). "Upregulated in the context of lung fibrosis are several collagens and proteoglycans, such as decorin, lumican, versican, and glycosaminoglycans." (PMID 41362624, 2025). "In its soluble form, DCN has been proposed to prevent lung fibrosis in severe COVID-19 by engaging the receptor of interferon regulatory factors (IRFs), thereby protecting epithelial cells from apoptosis and also neutralizing TGF-β, a strong fibrosis mediator." (PMID 39767799, 2024). "Studies have shown a reduction of decorin in different fibrotic organs, as in cardiac fibrosis following myocardial infarction and in acute exacerbation-idiopathic pulmonary fibrosis (IPF)." (PMID 33262766, 2020). "Fibroblasts from lung fibrosis patients have shown an increased production of small proteoglycans, with decorin as the major proteoglycan produced with implications in pulmonary fibrotic responses." (PMID 31426504, 2019). "Increased accumulation of versican and decorin has been also reported in patients with pulmonary fibrosis." (PMID 26751072, 2016). "In a subsequent study, it was shown that fibroblasts from patients with pulmonary fibrosis produced relatively more decorin compared to the total proteoglycan content than control subjects." (PMID 20459817, 2010). "In summary, stem cells overexpressing DCN can improve the local cellular microenvironment in pulmonary fibrosis by regulating local and systemic inflammation levels and ultimately reducing fibrous deposition to achieve the effect of treating pulmonary fibrosis." (PMID 40438789, 2025). "As seen in our previous studies on lung fibrosis, DCN was elevated in severe COVID-19 patients." (PMID 39767799, 2024). "In this study, we investigated whether ESM stimulates DCN secretion as an endogenous mediator and ameliorates pulmonary fibrosis." (PMID 39234595, 2024). "Animal experiments in decorin-null mice with myocardial infarction or in hamster and mice models of lung fibrosis showed both decorin requirement for proper fibrotic evolution of tissue injury and the potential therapeutic anti-fibrotic effect of decorin administration." (PMID 33262766, 2020). "Subsequently, decorin has been shown to reduce lung fibrosis induced by TGF-β1." (PMID 23406566, 2013).